EGFR (epidermal growth factor receptor)
Diseases named in the same sentence as EGFR in open-access papers (continued):
Sharing a sentence is not in itself a finding about the gene and the disease.
lung cancer (continued). "Interestingly, EGFR-TKI-resistant cells had drastically reduced cell survival and migration after treatment with the SFK inhibitor dasatinib, demonstrating that Src inhibitors may overcome EGFR inhibitor resistance in lung cancer cells." (PMID 36902280, 2023). "The silencing of FAM83A can inhibit the proliferation, invasion and migration of lung cancer cells, which may be related to the inhibition of epidermal growth factor receptor (EGFR)/mitogen activated protein kinase (MAPK)/choline kinase α (CHKA) signal transduction and activation." (PMID 37907984, 2023). "However, the relationship between LAMC2 and EGFR in lung cancer remains elusive." (PMID 37542131, 2023). "This suggests that EGFR-mutant lung cancers retain sensitivity to EGFR-TKIs upon retreatment; subsequent targeted therapy after failure of adjuvant targeted therapy may provide longer OS and may be a better sequential treatment model for patients with resected EGFR mutation NSCLC." (PMID 37528390, 2023). "Furthermore, EGFR-RPA performed better in terms of calibration than other prognostic indices.BM progression after TKI and EGFR mutation type were specific prognostic factors for EGFR-mutated lung cancer BM." (PMID 37020869, 2023). "For example, EGFR-mutated NSCLC frequently responds better to treatment with EGFR-TKIs, such as gefitinib and erlotinib, which have significantly improved the outlook for lung cancer patients and given them new hope, but their efficacy has been hampered by the emergence of acquired drug resistance." (PMID 38169723, 2023). "However, the association of 8PN‐dependent EGFR signaling and ER in lung cancer has not yet been clarified in this study." (PMID 37013960, 2023). "Mechanistically, long-term exposure of lung cancer cells to PM2.5 may promote lung cancer progression through activation of the Aryl hydrocarbon receptor (AhR) and epidermal growth factor receptor (EGFR), which boosts the Serine protease pathway transmembrane 2 (TMPRSS2)-IL8 pathway." (PMID 38299096, 2023). "This cohort study enrolled 1374 lung cancer patients with no detected EGFR and ALK mutations." (PMID 36969059, 2023). "To explore whether 3 years of cumulative PM2.5 exposure is associated with lung cancer in an independent cohort not restricted to EGFR-driven cases, we obtained data from 407,509 participants in the UK Biobank." (PMID 37020004, 2023). "Therefore, in other types of cancer with a brain tumor or possible brain metastasis such as glioblastoma and lung cancer, the existence of EGFR‐LFD might be taken into consideration during the EGFR‐targeted treatment management." (PMID 36622089, 2023). "Besides JAK1, mutant EGFR mediates MUC1-CT expression in the transgenic lung cancer mouse model." (PMID 36810913, 2023). "In non–small cell lung cancer patients with epidermal growth factor receptor (EGFR) mutations, the efficacy of atezolizumab‐bevacizumab‐carboplatin‐paclitaxel (ABCP) therapy and platinum‐based chemotherapy after EGFR‐tyrosine kinase inhibitor was found to be equivalent in real‐world setting." (PMID 36866788, 2023). "In addition, AXL overexpression is found to enhance DTC survival in EGFR‐mutant lung cancer." (PMID 37638338, 2023). "Furthermore, upregulation of sialylation and fucosylation may reduce EGFR-mediated lung cancer cell invasion." (PMID 37724903, 2023). "Furthermore, TMB was lower in EGFR-mutant lung cancer than in EGFR wild-type lung cancer." (PMID 35871700, 2023). "In addition, exosomal membrane surface proteins such as EGFR, placental alkaline phosphatase, epithelial cell adhesion molecule (EpCAM), and Alix are significant predictors of long-term overall survival in lung cancer patients and can be used as potential prognostic markers." (PMID 37122754, 2023).
lung cancer (continued). "MMP11 expression was higher in lung cancer tissue than in normal tissue (normal, n = 59, yellow), regardless of EGFR mutation status, according to a comparison of 512 LUAD samples with identifiable EGFR mutations information in the TCGA database and 59 normal lung tissue samples." (PMID 36756152, 2023). "In addition, JAC4 phosphorylated and stabilized NEDD4L by JWA-triggered activation of the AMPK-signaling pathway; the phosphorylation of NEDD4L further accelerated the degradation of EGFR through enhanced ubiquitination at K716, therefore suppressing the progression of EGFR-driven lung cancer." (PMID 37240137, 2023). "However, unlike lung cancer and other tumors, EGFR gene mutations are uncommon in colorectal malignancies." (PMID 37692610, 2023). "Of note, previous studies showed that complete response (CR) could be achieved in early-stage lung cancer with EGFR-TKIs as neoadjuvant treatment, whereas EGFR-TKIs rarely induced CR among patients with advanced NSCLC, for which a highly immune suppressive microenvironment was established." (PMID 36817465, 2023). "Then we queried if AICAR could also target EGFR wild-type lung cancer cell-derived tumours." (PMID 36810913, 2023). "Notably, AXL–induced EMT transition is a common occurrence in many TKI–resistant lung cancers, including those resistant to Osimertinib, a third–generation EGFR–TKI that may induce AXL." (PMID 37834326, 2023). "Common NSCLC driver genes, such as epidermal growth factor receptor, anaplastic lymphoma kinase, and c-ros oncogene 1-receptor tyrosine kinase, are corresponding molecular targeted drugs, which can significantly prolong the disease control time and OS in patients with lung cancer." (PMID 37124525, 2023). "Consequently, the phytochemicals CBDA, CBD, THCV, Δ-9-THC, Δ-8-THC, CBL, THCA, BCP, and γ-Ele discussed in this study could be employed as structural keys for the development of new drugs that act as EGFR-TKIs for breast and lung cancer." (PMID 37128337, 2023). "Notably, IL-1β release and inflammation are also considered the driving force in silica- and asbestos-induced lung cancer, but EGFR mutations appear to be less frequent in never-smokers occupationally exposed to such mineral particles." (PMID 37696458, 2023). "Young patients with lung cancer have unique clinicopathological and gene mutation characteristics, such as common in women, no smoking history, mainly adenocarcinoma, with advanced TNM stage, and prevalence of targeted genetic alterations such as ALK gene and EGFR gene mutations." (PMID 37009049, 2023). "Gene expression correlation analysis of 207 human lung cancer cell lines using the DepMap data explorer revealed that GRP78 is positively correlated with EGFR at the mRNA level (P = 2.4e-13, R = 0.48), suggesting that GRP78 may regulate EGFR expression at the transcriptional level." (PMID 37487081, 2023). "In addition, the levels of exosomal EGFR levels were significantly higher in five out of nine lung cancer patients when compared to healthy individuals while the levels of soluble EGFR in plasma were not significantly different in seven out of nine lung cancer patients." (PMID 36834471, 2023). "At present, folic acid receptors (FARs), sigma receptors, transferrin receptors (TfRs), EGFR, urokinase plasminogen activator receptors (uPARs), etc., which are overexpressed on the surface of lung cancer cells, have been applied in targeted drug delivery for lung cancer." (PMID 36986849, 2023). "We then asked if simultaneously targeting MUC1 and EGFR could improve lung cancer treatment." (PMID 36810913, 2023).
lung cancer (continued). "According to current International Association for the Study of Lung Cancer guideline, physicians may first use plasma cell‐free DNA (cfDNA) methods to identify epidermal growth factor receptor (EGFR) tyrosine kinase inhibitor (TKI)‐resistant mechanisms (liquid rebiopsy) for lung cancer." (PMID 38140788, 2023). "Some patients with lung cancer harboring EGFR mutations do not smoke." (PMID 38067382, 2023). "In a meta-analysis, Mao and colleagues showed an ORR of 3% (6/210) in patients with mutant KRAS NSCLC and of 26% (287/1125) in KRAS wt lung cancers, fulfilling the hypothesis that KRAS mutations represent negative predictive biomarkers for tumor response in NSCLC patients treated with EGFR-TKIs." (PMID 36077640, 2022). "In the present study, we designed a novel strategy for the treatment of lung cancer using low-dose radiotherapy to increase vascular permeability and promote the targeted accumulation of drug-loaded NPs, which resulted in a superior antitumor effect through EGFR-mediated endocytosis." (PMID 35156493, 2022). "Furthermore, EGFR expression is up-regulated in the pleural endothelial cells of patients with lung cancer having malignant pleural effusions, and VEGF-A is expressed in exosomes in malignant pleural effusions, increasing proliferation, angiogenesis, and vascular permeability in pleura." (PMID 36438852, 2022). "Data, mainly from BC, lung cancer, and glioma have suggested many potential mechanisms related to aberrant EGFR signaling, such as high ligands and receptors expression, autocrine signaling loops, constitutive activation of EGFR mutants and crosstalk with other receptors." (PMID 36428610, 2022). "EGFR mutations were more common in people who never smoked than in smokers, with an incidence of 45% mutations in never-smokers and 7% in tobacco associated lung cancer." (PMID 35497180, 2022). "However, second-generation EGFR-TKIs were not able to be administered at full strength to inhibit T790M mutant lung cancer due to adverse side effects, such as rash caused by inhibition of normal cells." (PMID 35223483, 2022). "Therefore, their inhibitory effects on EGFR activity were evaluated by performing an ELISA to measure the phosphorylation level of the autophosphorylation site (i.e., the EGFR Y1068 residue) in gefitinib-resistant H1975 lung cancer cells." (PMID 35408854, 2022). "However, lung cancer still leads cancer mortality, and non-small-cell lung carcinoma patients with mutant EGFR cannot benefit from checkpoint inhibitors due to toxicity, relying only on palliative chemotherapy and the third-generation tyrosine kinase inhibitor (TKI) osimertinib." (PMID 35347108, 2022). "Lung cancer patients harboring EGFR mutations have a good prognosis (results not shown), which may have influenced the prognosis in females." (PMID 34170380, 2022). "Importantly,more comprehensive clinical studies also support this notion that EGFR mutations in lung cancer are not necessarily confinedto the kinase domain." (PMID 36148499, 2022). "Moreover, previous reports have indicated that ER signaling plays an important role in primary lung cancer following breast cancer, and that activation of ER signaling occurs through EGFR/HER-1, thus confirming a correlation between ER expression and EGFR mutation." (PMID 36313724, 2022). "Thus, we hypothesize that CXCL10/CXCR3/Src activation may mediate an oncogenic signaling pathway in EGFR-mutant lung cancer cell lines." (PMID 36612121, 2022). "Likewise, a study involving 7858 lung cancer patients which compared mutations between patients aged ≤45 vs >45 years observed a higher prevalence of ALK, ROS1 and RET fusions, ERBB2 exon-20 insertions and EGFR exon-19 deletions in younger patients." (PMID 36263208, 2022).
lung cancer (continued). "Moreover, activation of the A2B receptor promotes the recovery of irradiated lung cancer cells from DNA damage by the mediation of the γ-radiation-induced translocation of EGFR and phosphorylation of src and EGFR, while A2B inhibition is a therapeutic approach to make cancer cells radiosensitive." (PMID 36230484, 2022). "Since cells harboring KRAS mutation are the main reason for EGFR-TKI resistance with the continuous expression of KRAS, we speculated that the combination treatment of MA and EGFR-TKI osimertinib was a strategy to inhibit KRAS-mutated lung cancer cells." (PMID 36712673, 2022). "Epidermal growth factor receptor (EGFR) genotyping and programmed death ligand-1 (PD-L1) expressions are of paramount importance for treatment guidelines such as the use of tyrosine kinase inhibitors (TKIs) and immune checkpoint inhibitors (ICIs) in lung cancer." (PMID 35250988, 2022). "Taken together, these data suggest that SALL4 targeting may represent a valid therapeutic approach and particularly valuable for EGFR-mutation negative lung cancer cases." (PMID 36010677, 2022). "However, inhibition of the EGFR pathway could partially contribute to the antitumor action of EGCG in lung cancer." (PMID 35402265, 2022). "Moreover, accumulating evidence has demonstrated that aberrant expression of individual ncRNAs dramatically correlates with TNM stage, treatment response and even prognosis of EGFR TKI-resistant lung cancer, highlighting their potential as prognostic, predictive and therapeutic biomarkers." (PMID 36139582, 2022). "Notably, lung cancer cells from clinical samples contained a significantly higher percentage of ALDH1A1+ cells that were resistant to epidermal growth factor receptor (EFGR) trypsin kinase inhibitor (TKI) and chemotherapy, manifesting one of the fundamental properties of CSCs." (PMID 35053430, 2022). "Notably, results of a meta-analysis indicate that lung cancer in non-smokers seems to be a distinct disease caused by mutations in driver genes, such as those for the epidermal growth factor receptor (EGFR) and anaplastic lymphoma kinase (ALK)." (PMID 36358986, 2022). "In addition, in lung cancer patients with wild-type EGFR, lower levels of ADAMTS8 might be of a survival benefit compared with higher levels." (PMID 35743687, 2022). "The most common driver mutation of lung cancer in East Asian never-smokers is EGFR mutation." (PMID 35740676, 2022). "The EGFR nuclear translocation in lung carcinogenesis was associated with better prognosis in our previous study; therefore we reason that HPV oncoproteins may interfere with EGFR nuclear trafficking and may change lung cancer behavior related to more sensitivity to cisplatin." (PMID 36358752, 2022). "Therefore, we investigated whether MA, a proven natural inhibitor of PLA2, could inhibit KRAS-mutated lung cancer cells to find a new therapeutic approach for EGFR-TKI-resistant lung cancer cells." (PMID 36712673, 2022). "Mutations in lung cancer driver genes (KRAS, EGFR, BRAF, ALK, ROS1, MET, RET, and ERBB2) in the high- and low-risk groups were shown on a waterfall plot, which demonstrated that the low-risk group (20%) harbored a higher EGFR mutation frequency than did the high-risk group (8%)." (PMID 36353226, 2022). "In addition, afatinib has been shown to inhibit the growth of gefitinib-resistant lung cancer cells harboring low levels of EGFR T790M mutation, but not those with high levels of EGFR T790M mutation." (PMID 36232650, 2022). "An increased frequency of EGFR T790M detection correlated with tumor progression/ metastasis by liquid biopsy and is explained by low copy number in peripheral blood in early stage, that may pose problems for early screening of lung cancer by liquid biopsy." (PMID 35209919, 2022). "However, there is a lack of investigation about the EGFR mutation among Iranian patients with lung cancer, influencing the selected therapeutic plan." (PMID 35463723, 2022).
lung cancer (continued). "Moreover, despite adenocarcinomas showing the highest EGFR mutation rate among all histological cancer types, we included all patients with lung cancer, unlike other studies that exclusively selected patients with NSCLC or adenocarcinoma." (PMID 35912248, 2022). "To verify whether the early emergence of resistant clones could predict the final resistance mechanism in other lung cancer cell models, we investigated a cell line (NCCLu-15) derived from a treatment-naïve 65-years-old female NSCLC patient with EGFR mutation." (PMID 35326664, 2022). "Furthermore, fibroblast growth factor receptor (FGFR) and IL-6 signaling work in a concerted manner to activate STAT3 following erlotinib treatment in EGFR-mutant lung cancer cells, contributing to the resistance of drug-treated “oncogene-addicted cancer cells”35." (PMID 35228642, 2022). "On the other hand, EGFR blockers—including small kinase inhibitors such as erlotinib, gefitinib, or afatinib, or monoclonal antibodies—have been used in several human proliferative disorders, including lung cancer, opening novel opportunities to use EGFR blockers in renal diseases." (PMID 35204752, 2022). "Sex disparities have been documented in lung cancer incidence and sex may also influence treatment outcomes (such as in the case of epidermal growth factor receptor inhibitors and anti-programmed cell-death protein 1 (PD1) inhibitors) or treatment complications." (PMID 36354697, 2022). "Although EGFR is reported to be a major driver oncogene in lung cancer in Asia, especially adenocarcinoma, the exact proportion of Chinese NSCLC patients with EGFR mutations varies by report, and the difference may be related to the limited number of patients previously evaluated." (PMID 35265073, 2022). "Therefore, it is important to consider other potential biomarkers that could be indicative of the EGFR to SCLC transformation, such as germline mutational analysis, with germline mutations in lung cancer becoming more commonly detected." (PMID 35268520, 2022). "Moreover, in lung cancer, gefitinib (Iressa), an anticancer drug that inhibits the epidermal growth factor receptor (EGFR), was shown to increase the intracellular translocation of exosomes, but decrease that of liposomes, which are typically used for drug-delivery systems." (PMID 36361760, 2022). "As one of the most important pathological types of lung cancer, in recent years, individualized lung adenocarcinoma treatments, including EGFR TKIs and EML4‐ALK, have been highly effective for the treatment of patients with EGFR mutations or harboring EML4‐ALK fusions." (PMID 34854250, 2022). "Therefore, our study explored the role of EGFR inhibitors (afatinib and allitinib) and conducted a comprehensive in vitro and in silico analysis of the molecular mechanisms triggered by KRAS mutations in a panel of lung cancer cell lines." (PMID 35887120, 2022). "RET fusion may be responsible for the pathogenesis in patients with lung cancer without mutations in EGFR, ALK, or ROS1, which may be related to the RET-induced promotion of apoptosis resistance." (PMID 35211155, 2022). "Compared with stage-IIIB/IV lung cancer patients with pan-negative driver mutations (OS 12.3 months), those with mutations of EGFR (OS 22.5 months) or ALK (OS 21.9 months) experienced better OS; while KRAS mutations (OS 6.4 months) were associated with poor OS." (PMID 35713442, 2022). "Together, our findings indicate that HPV oncoproteins might change the behavior of lung cancer cells through changes in EGFR nuclear trafficking, and the expression of HPV 16E6/18E6 and EGFR serves as a predictive biomarker of survival benefits in lung adenocarcinoma patients." (PMID 36358752, 2022).